ENSG00000201660
Synonyms: LOC124900497
Gene: Small nucleolar RNA gene on chromosome X (5,410,122 to 5,410,251, forward strand). Ensembl gene ENSG00000201660.
Gene Ontology:
Biological process: RNA processing
Cellular component: nucleolus
Homologues: Orthologues: mouse Gm24615 (61% identical). Paralogues in human: SNORA20 (78% identical), SNORA20B (77% identical).